TET2 (tet methylcytosine dioxygenase 2)
Diseases named in the same sentence as TET2 in open-access papers (continued):
Sharing a sentence is not in itself a finding about the gene and the disease.
infection (continued). "Recent studies show that infection-induced inflammation is critical for the onset of malignance in TET2-/- mice, shedding light on the clinical prevention and treatment of malignancy related to TET2 deficiency." (PMID 34512655, 2021). "Jointly, these data indicate that Tet2 acts as an inhibitory regulator of gene expression of several cytokines and chemokines in cells exposed to stimuli with relevance for infection." (PMID 35011643, 2021). "In EBi3-/- mice, infection caused an increase in DNA demethylation and analyzing EBi3-/-C versus EBi3-/-I we can see that TET1 plays the major differences observed in S2, but TET2 and TET3 also increased strongly their expression values." (PMID 32078636, 2020). "The change of proliferation capacity of stable cell strains, TET2, miRNA-22-3p/5p siRNA infection was detected by CCK-8 method." (PMID 29029424, 2017). "Other epigenetic modulators like DNA demethylases TET2 and TET3, histone variant genes, INO80 complex, PRC2 complex genes, EED and SUZ12 were also associated with DNA methylation changes upon infection." (PMID 27112593, 2016). "The mRNA-expression levels of both TET2 and N protein significantly increased after infection." (PMID 40697650, 2025). "Similarly, ALV-J infection in HD11 cells showed a significant rise in TET2 protein expression at 24 h post-infection, followed by a decline at 36 and 48 h." (PMID 39840982, 2025). "In addition, research has shown that the avian influenza virus (IAV) degrades TET2 mRNA to suppress its expression during infection." (PMID 39840982, 2025). "Furthermore, TCID50 assays conducted 48 h post-infection demonstrated substantially elevated virus titers in TET2-KO cells relative to TET2-WT cells." (PMID 39840982, 2025). "The results demonstrated minimal changes in TET2 mRNA expression between 0 and 12 h post-infection." (PMID 39840982, 2025). "Taken together, these data support the notion that defects in Tet2 promote a hyper-inflammatory immunogenic profile that may contribute to worse outcomes of infections and other CHIP comorbid conditions." (PMID 38573824, 2024). "We found that MDS patients with DM have a higher frequency of TET2 and SF3B1 mutations and an inferior prognosis, which may be caused by the higher incidence of infection." (PMID 38305890, 2024). "The combined impact of TET2 mutation on reduced NET antimicrobial capacity and increased lifespan may further shift the balance toward pathology by extending the course of infection while interfering with NET clearance." (PMID 37267914, 2023). "Removal of Tet2 and Tet3 by infection with AAV8-cre at 3 weeks was able to inhibit demethylation at these sites, but regions that had already undergone demethylation prior to AAV8-cre administration remained largely hypomethylated in these animals (<6% increase)." (PMID 29795194, 2018). "Analysis of Tet2-deficient (Tet2fl/flCd4-cre) CD8 T cells responding to infection with lymphocytic choriomeningitis virus (LCMV) showed increased LCMV gp33-specific memory precursor cells (KLRG1− CD127+) and decreased short-lived effector cells (KLRG1+ CD127−) on day 8 post-infection." (PMID 30809228, 2019). "Western blot results indicated that at later stages of infection, the expression of ALV-J Env protein was higher in TET2-KO cells compared to TET2-WT cells, suggesting a significant increase in ALV-J replication." (PMID 39840982, 2025). "We thought that the ability of Bobcat339 to prevent the infection and replication of SARS-CoV-2 not only followed the TET2-hm5C pathway but also directly blocked the functions of several crucial SARS-CoV-2 proteins." (PMID 40697650, 2025). "Overall, our study revealed that TET2 and SARS-CoV-2 presented positive feedback to increase SARS-CoV-2 replication and infection efficiency in an in vitro epigenetic drug screening of a hiPSC-CM model." (PMID 40697650, 2025).
infection (continued). "A pro-inflammatory environment is also observed post-infection or after TNF-α administration in animal models, and presumably favors the proliferation of TET2-mutant stem cells, triggering a higher proportion of circulating TET2-mutant immune cells." (PMID 36835370, 2023). "To further investigate whether TET2 expression levels were correlated with infection duration and viral load, we analyzed the mRNA-expression levels of N protein (a marker of SARS-CoV-2) and TET2 in hiPSC-CMs 6 and 24 h postinfection." (PMID 40697650, 2025). "In addition, when the expression of TET2 in HepG2-NTCP was depleted, HBV RNAs, HBcAg, and rcDNA levels increased at 6 days post-infection." (PMID 38048324, 2023). "To evaluate a possible role of myeloid cell Tet2 herein we measured the plasma of AST, ALT (both reflecting hepatocellular injury) and LDH (reflecting cell injury in general), and evaluated lung injury by assessing lung histopathology 16 h after infection." (PMID 35011643, 2021). "In the non-ECs fraction, Ad-P4HA1 infection slightly increased the P4HA1 protein level but did not change the protein levels of FBP1 and TET2." (PMID 38238754, 2024). "Furthermore, Ad-shP4HA1 infection did not affect protein levels of P4HA1, TET2, and FBP1 in the non-ECs fraction." (PMID 38238754, 2024). "Furthermore, the qRT-PCR analysis demonstrated a significant upregulation of TET1 but not TET2 and TET3 mRNA expression in normal gastric epithelium and GC cells after H. pylori (26695 and SS1) infection (P < 0.0001)." (PMID 37016382, 2023). "In the study, we have demonstrated that the absence of TET2 significantly weakens the innate immune response in host cells, particularly affecting the RIG-I-like receptor pathways, resulting in a significant increase in ALV-J replication during the later stages of infection." (PMID 39840982, 2025).
hematological cancers (26 papers, 2013 to 2025). "Corresponding to this result, among the TET family genes, TET2 mutations are common in hematologic cancers, which are found in myeloid and lymphoid malignancies." (PMID 40599235, 2025). "Tet methylcytosine dioxygenase 2 (TET2) is one of the most common mutations in haematological neoplasms." (PMID 35279121, 2022). "In the early stage, patients with germline TET2 mutations present with single lineage cytopenia for a long time and eventually develop haematological neoplasms under the second hits of other gene mutations." (PMID 35279121, 2022). "Apart from the loss-of-function mutations, aberrant expression levels of TET2, although less frequent, have also been observed in hematological cancers." (PMID 36059621, 2022). "This suggests that germline TET2 mutations are predisposed to haematological tumours under the second hit of other gene mutations." (PMID 35279121, 2022). "Shuai Jiang discusses the regulation and functional role of the Tet2 enzyme, a regulator of lymphoid and myeloid cell development frequently mutated in haematopoietic cancers." (PMID 33184433, 2020). "TET2 catalyses DNA demethylation and is mutated in various blood cancers; in particular Tet2 null mice develop haematological neoplasms." (PMID 28440315, 2017). "Hematological cancers are characterized by recurrent mutations in genes involved in the regulation of DNA methylation, notably TET2, IDH1/2 and DNMT3A." (PMID 25901663, 2015). "Mutations in TET2 linked with a decrease in 5-hmC levels were found in hematological cancers." (PMID 35269864, 2022). "Mutations in TET2 associated with a decrease in 5-hmC levels were found in hematological cancers." (PMID 35269864, 2022). "TET2 is frequently mutated in the majority of hematologic cancers, with a frequency of 17–37% in myeloid and 15–33% in T-cell lymphoid malignancies, and the disruption of its PPIs by mutations can be an important mechanism of its pathological role in these cases." (PMID 33395407, 2021). "TET2-inactivating mutations result in a decrease of 5-hydroxymethylcytosine, and this parameter has been proposed as a potential diagnostic and prognostic marker for hematological cancers." (PMID 32188030, 2020). "This review discusses Tet2-related profiles in hematopoietic cancers, different subtypes of adaptive and innate immune cells, and Tet2 regulation by various interactors." (PMID 33184433, 2020). "ARCH/CHIP is mainly associated with mutations in three epigenetic regulatory genes—DNMT3A, TET2, and ASXL1—that have been implicated in hematologic cancers and is a strong risk factor for subsequent hematological cancers." (PMID 33292805, 2020). "It will also be crucial to determine the relationship between Tet2 interactors in Tet2 dysregulation of the progression of non-hematopoietic cancers and blood cancers." (PMID 33184433, 2020). "It is well known that age-related clonal hematopoiesis is associated with increase in the risk of hematologic cancer and the majority of the variants occurred in three genes: DNMT3A, TET2, and ASXL1." (PMID 29619119, 2018). "TET2 and DNMT3A mutations likely occur early during evolution of hematopoietic neoplasms and are even detectable in apparently healthy individuals." (PMID 29148847, 2018). "CH is associated with increased risk of therapy-related hematologic malignant neoplasms, and genes frequently mutated in CH such as DNMT3, TET2, PPM1 are also commonly altered in hematologic malignant neoplasms." (PMID 30705875, 2018). "Since TET2 is the main regulator of 5-hmc in hematological cancers, TET2 expression was also studied in lymph node biopsies (TET2)." (PMID 28881727, 2017). "Thus, reduced TET2 function, due to loss-of-function mutations, reduced mRNA expression due to epigenetic silencing or not yet elucidated mechanisms may have a great contribution to the malignant phenotype of hematological cancers." (PMID 26984174, 2016).
hematological cancers (continued). "TET2 exhibits varying mutation rates in CHIP and different hematologic cancers." (PMID 40599235, 2025). "It was suggested that TET2 gene-targeting miRs, such as miR-26a/b, may play oncogenic roles in hematopoietic cancers." (PMID 33519805, 2020). "This difference indicates that germline TET2 mutation alone may not be sufficient to initiate haematological neoplasms, and other gene comutations may be necessary for initiation." (PMID 35279121, 2022). "However, the difference in median age between the two MDS subgroups was not significant, which may indicate that patients with germline TET2 mutations need a long incubation period to develop MDS or other haematological tumors, such as the germline DDX41 mutation in haematological neoplasms." (PMID 35279121, 2022).
blood cancers (20 papers, 2014 to 2025). "We perform a deep, multi-omics characterization (epigenome, transcriptome, and proteome) of HSCs in a mouse model carrying a loss-of-function mutation in Tet2, a driver of increased self-renewal in blood cancers." (PMID 41447537, 2025). "Although TET2 mutations are prevalent in hematologic neoplasms, TET2 mutation alone is insufficient to potently drive hematopoietic transformation." (PMID 36675240, 2023). "Mutations in the DNMT3A, ASXL1, and TET2 genes can contribute to the development of blood cancer, and are frequently found in MDS and AML patients." (PMID 37726289, 2023). "We also identified a potential biomarker: two or more pathogenic TET2 mutations with high mutation burden for the development of second hematologic neoplasm in AITL patients." (PMID 34581268, 2021). "One of the features shared among the four cases with concomitant hematologic neoplasms is that they all had multiple (>1) pathogenic mutations in TET2." (PMID 34581268, 2021). "Therefore, to understand the clonal structure, proliferative, and differentiation capacity of neoplastic cells in the hematologic neoplasm, and identification of loss‐of‐function variants in TET2 is crucial." (PMID 37601840, 2023). "Tet2 mutations drive tumorigenesis in several blood cancers as well as in solid cancers." (PMID 33184433, 2020). "In our study, we found that the difference in TET2 dysfunction between solid tumours and blood cancers is mainly due to differences in the cellular environment." (PMID 37620362, 2023). "It is important to emphasize that the development of cardiovascular diseases can be initiated by mutations associated with blood cancer (DNMT3A, JAK2, ASXL1, and TET2)." (PMID 37726289, 2023). "The last decade of research has shed light on the complex biological functions of TET2 in normal hematopoiesis and blood cancer development." (PMID 35159097, 2022). "This review summarizes the latest molecular findings regarding TET2 functions in hematopoietic cells and their potential implications in blood cancer origin and evolution." (PMID 35159097, 2022). "This review focuses on recent advances in characterizing the main TET2-mediated molecular mechanisms that activate aberrant transcriptional programs in blood cancer onset and development." (PMID 35159097, 2022). "Our study presented one such case (patient #20) whose AITL developed after 10 years of PV and the two hematologic neoplasms shared three identical JAK2 and TET2 mutations." (PMID 34581268, 2021). "Here I discuss recent studies that elucidate mechanisms and biological consequences of Tet2 dysregulation in blood cancers." (PMID 33184433, 2020). "Specifically targeting Tet2 or its downstream molecular signaling pathways might offer novel therapeutic strategies for blood cancer prevention." (PMID 33184433, 2020). "Therefore, the mechanism of TET2 dysfunction in solid tumours may be different from that in blood cancers." (PMID 37620362, 2023). "Given that most patients with hematologic neoplasms are TET2 haplodeficient and that TET1 and TET3 mutations are rare, it is likely that activating the residual TET2 or the other TET family members TET1 and TET3 may be a promising treatment strategy for TET2-deficient malignancies." (PMID 36979633, 2023). "Establishing new mouse models, to delete Tet genes at various developmental stages and at specific T cell subsets will shed light on the precise biological roles of TET2 and TET3 in immune response and blood cancer development." (PMID 35990681, 2022). "Although cumbersome, this approach led to the successful introduction of clinically relevant mutations in a variety of genes, including DNA methyltransferase 3 alpha (Dnmt3a) and tet methylcytosine dioxygenase 2 (Tet2), within HSPC, and their introduction to mice to establish blood cancer models." (PMID 34395722, 2021).
cardiac disease (5 papers, 2020 to 2025). "Since in murine models of cardiac disease Tet2- and Dnmt3A-loss of function activated the inflammasome complex and promoted fibrosis development, it is conceivable that Dnmt3A or Tet2-CHIP-driver mutations contributed to the development of AVS." (PMID 40278194, 2025). "Notably, IDH1 and IDH2 mutations also occur as CHIP mutations and mechanistically lead to conversion of αKG to R-2HG, which is a proven oncometabolite and a potent inhibitor of TET2, suggesting a common pathway of CHIP induced cardiac disease." (PMID 32948843, 2021).
neurodegenerative disease (5 papers, 2020 to 2021). A disorder of the central nervous system characterized by gradual and progressive loss of neural tissue and neurologic function. "A recent study demonstrated rare coding and noncoding variants in TET2 to be associated with different forms of neurodegenerative disease including FTD." (PMID 34561610, 2021). "Nevertheless, it cannot be discarded that neuronal TET2 mutations could also be the reason for increased neurodegenerative disease risk or even a combined effect in microglia and neurons." (PMID 32709045, 2020). "These include a locus on chromosome 4q24, which encompasses TET2, a gene encoding a DNA demethylase with known roles in the microglial inflammatory response and neurodegenerative diseases;77,78 and a locus on chromosome 13q31.2, which encompasses LINC00433 but no protein-coding gene." (PMID 32699239, 2020). "Thus, TET2 mutations are associated with multiple neurodegenerative diseases and variations of the TET2 gene in either non-coding or coding regions might cause alterations of the homeostasis of key aging-related processes." (PMID 33804473, 2021). "Notably, the relevance of TET2 in neurodegenerative diseases has come to attention in a recent paper published by Cochran and colleagues." (PMID 32709045, 2020).
infectious disease (4 papers, 2022 to 2025). A disorder directly resulting from the presence and activity of a microbial, viral, or parasitic agent in humans. "In vitro, macrophages with TET2-repressing mutations expressed the pro-inflammatory IL-1β, IL-6 and inflammasome NLRP3 in a pattern typically associated with macrophage activation in infectious diseases." (PMID 36835370, 2023). "Furthermore, targeting TET2-associated pathways and TET inhibitors may represent a novel approach in drug development for the treatment of severe emerging infectious diseases, including SARS-CoV-2 infection." (PMID 40697650, 2025).
inflammation (4 papers, 2021 to 2025). Aberrant reaction of the microcirculation characterized by movement of fluid and leukocytes from the blood into extravascular tissues. "In association with lower levels of brain inflammation at the subacute timepoint, it was also observed that the extent of reactive astrogliosis surrounding the lesion was smaller in mice transplanted with Tet2-KO BM cells." (PMID 39742155, 2024).
metabolic disease (4 papers, 2020 to 2024). A congenital disorder (due to inherited enzyme abnormality) or acquired (due to failure of a metabolically important organ) disorder resulting from an abnormal metabolic process. "Both the TERT mutation (rs7705526) and the TET2 (rs2454206) are reported to significantly correlate with levels of blood pressure in the Common Metabolic Diseases Knowledge Portal (hugeamp.org)." (PMID 36009574, 2022). "Therefore, TET2 is supposed to be capable of maintaining cell size and metabolic homeostasis and providing protection against tumorigenesis and metabolic disorders by suppressing mTORC1 activity in normal cells." (PMID 37550284, 2023). "However, the potential of TET2 modulation in vivo for treating metabolic disease remains unclear." (PMID 39872508, 2024).
adenocarcinoma (3 papers, 2023 to 2024). A common cancer characterized by the presence of malignant glandular cells. "We measured protein expression of Tet2 in both adeno and NE-like PCa cell lines by western blotting and found that TET2 expression is increased in NE-like cell lines compared to adenocarcinoma." (PMID 38168280, 2023). "Conversely, TET2 was predominantly expressed in adenocarcinomas (BRCA, COAD, READ, and THCA)." (PMID 39104395, 2024).
bacterial infection (3 papers, 2022 to 2024). "Similarly, loss of TET2 in innate lymphoid cells results in less efficient immune response against bacterial infection." (PMID 35990681, 2022).
neurological diseases (3 papers, 2017 to 2024). "Mutations and altered expression of Dnmt1 and Tet2 are associated with age-related cognitive decline and neurological diseases." (PMID 31649729, 2019). "Recently, in TDG-/- cells, TET2-induced 5-hmC accumulation was observed to result in GC > AT transitions, suggesting a mutagenic potential of 5-hmC metabolites if not removed/repaired and which may increase the risk of developing neurological disorders." (PMID 28218666, 2017).
CNS tumours (1 paper, 2023). "A total of 69 TET2 mutations identified in CNS tumours are currently documented in cBioPortal." (PMID 36989121, 2023).
gastrointestinal tumors (1 paper, 2015). "Recently, it was shown that succinate dehydrogenase (SDH) deficiency decreases the 5hmC level in gastrointestinal tumors by a metabolic inhibition of TET2 activity." (PMID 25918251, 2015).